RNF20 (ring finger protein 20)
Description:
Component of the RNF20/40 E3 ubiquitin-protein ligase complex that mediates monoubiquitination of 'Lys-120' of histone H2B (H2BK120ub1). H2BK120ub1 gives a specific tag for epigenetic transcriptional activation and is also prerequisite for histone H3 'Lys-4' and 'Lys-79' methylation (H3K4me and H3K79me, respectively). It thereby plays a central role inb histone code and gene regulation. The RNF20/40 complex forms a H2B ubiquitin ligase complex in cooperation with the E2 enzyme UBE2A or UBE2B; reports about the cooperation with UBE2E1/UBCH are contradictory. Required for transcriptional activation of Hox genes. Mediates the polyubiquitination of isoform 2 of PA2G4 in cancer cells leading to its proteasome-mediated degradation. (Microbial infection) Promotes the human herpesvirus 8 (KSHV) lytic cycle by inducing the expression of lytic viral genes including the latency switch gene RTA/ORF50.
Synonyms: hBRE1; BRE1A; FLJ20382; FLJ11189; KAIA2779; BRE1
Tractability: PROTAC: ubiquitination databases record sites on it; its protein half-life has been measured.
Gene: Protein-coding gene on chromosome 9 (101,533,853 to 101,563,344, forward strand). Ensembl gene ENSG00000155827.
Subcellular location: Nucleus
Subcellular location (Human Protein Atlas): Nucleoplasm; Cytosol
Pathways (Reactome):
Metabolism of proteins: E3 ubiquitin ligases ubiquitinate target proteins
Signal Transduction: RHOBTB1 GTPase cycle
Gene Ontology:
Molecular function: histone binding; histone H2B C-terminal K residue ubiquitin ligase activity; identical protein binding; mRNA 3'-UTR binding; protein binding; transcription coactivator activity; ubiquitin protein ligase binding; ubiquitin-protein transferase activity; ubiquitin protein ligase activity; chromatin binding; metal ion binding
Biological process: negative regulation of cell migration; positive regulation of DNA-templated transcription; positive regulation of transcription by RNA polymerase II; protein polyubiquitination; regulation of DNA-templated transcription; regulation of mitotic cell cycle; ubiquitin-dependent protein catabolic process; chromatin remodeling; protein ubiquitination
Cellular component: BRE1 E3 ubiquitin ligase complex; HULC complex; nucleolus; nucleoplasm; nucleus; ubiquitin ligase complex
Genetic constraint (gnomAD): Loss-of-function variants: 75 observed, 108.16 expected, observed/expected ratio (o/e) 0.69, 90% interval 0.57 to 0.84. The upper end of that interval is the gene's LOEUF score, 0.84, which puts it in group 3 of 6, group 1 being the genes least tolerant of losing a copy. Missense variants: 763 observed, 1,094.7 expected, observed/expected ratio (o/e) 0.7, 90% interval 0.66 to 0.74. Synonymous variants: 348 observed, 390.56 expected, observed/expected ratio (o/e) 0.89, 90% interval 0.81 to 0.97.
Homologues: Orthologues: chimpanzee RNF20 (100% identical), macaque RNF20 (100% identical), dog RNF20 (98% identical), rabbit RNF20 (98% identical), pig RNF20 (98% identical), mouse Rnf20 (98% identical), rat Rnf20 (97% identical), guinea pig RNF20 (95% identical), tropical clawed frog rnf20 (74% identical), zebrafish rnf20 (63% identical), Drosophila melanogaster Bre1 (46% identical), Caenorhabditis elegans rfp-1 (22% identical). Paralogues in human: RNF40 (59% identical).
Diseases named in the same sentence as RNF20 in open-access papers:
RNF20 is named in the same sentence as 56 diseases in open-access papers, as found by Europe PMC text mining. Sharing a sentence is not in itself a finding about the gene and the disease. The quoted sentences say what the papers report.
breast carcinoma (15 papers, 2016 to 2025). "In luminal breast cancer cells, however, RNF20 down-regulation was associated with a decrease in expression of ER gene targets that drive proliferation and migration including PGR, CXCL12 and FOXA1." (PMID 33233707, 2020). "RNF20 has been found to be highly expressed in breast cancer cell lines, and is tightly associated with tumorigenic and metastatic capacity of tumor cells." (PMID 33364200, 2020). "Consistent with this notion, RNF20 expression caused the increased CSC properties by activating the EMT program in breast cancer, indicating the importance of RNF20 in controlling the viability of CSCs." (PMID 33364200, 2020). "The RNF20 promoter has been reported to be hypermethylated in primary breast cancer cells and mutated at low frequency in colorectal cancer." (PMID 30669413, 2019). "(2015) they showed that RNF20/40 is physically associated with motor protein Eg5 and is functionally involved in spindle assembly in breast cancer cells." (PMID 29934362, 2018). "We also find that RNF20/40 and Eg5 are concurrently upregulated in human breast cancer samples and that high Eg5 expression is associated with worse overall survival of patients with luminal A, or B, breast cancer." (PMID 27557628, 2016). "Significantly, RNF20/40 and Eg5 are concurrently upregulated in human breast carcinomas and high Eg5 expression is associated with poorer overall survival of patients with luminal A, or B, breast cancer." (PMID 27557628, 2016). "To validate that the Snail-RNF20-G9a complex was associated with the E-cadherin promoter and mediated the transcriptional expression of the E-cadherin in breast cancer, we subsequently established stable clones with empty vector or RNF20 expression in MDA-MB231 and BT549." (PMID 33364200, 2020). "However, it is RNF20 that has been implicated as a modulator of DDR in breast cancer cells." (PMID 29934362, 2018). "Past observations made in hepatocellular carcinoma, mixed-lineage leukemia (MLL), HER2-driven mammary carcinoma, colorectal cancer and TNBC demonstrated an association between high RNF20 and RNF40 levels and worse cancer disease outcomes." (PMID 40597205, 2025). "This contrasts with the roles of these proteins in breast cancer cells, where both RNF20 and RNF40 promote carcinogenesis." (PMID 40436847, 2025). "A specific connection between RNF20/40 and cancer was also shown from studies of human breast cancer patient’s samples, as well as from in vivo experiments." (PMID 35954248, 2022). "Consistent with this, depletion of RNF20/40 in vitro resulted in spindle assembly defects, cell cycle arrest, and apoptosis, whereas depletion of either Eg5 or RNF20/40 in vivo suppressed breast cancer." (PMID 33199825, 2021). "Motivated by the expectation that additional nonhistone target proteins of RNF20/40 exist, we are currently seeking to identify EMT-TF-related proteins ubiquitylated by RNF20/40 or RNF40 in breast cancers." (PMID 33199825, 2021). "Decreases in H2Bub1 and RNF20/40 levels observed in certain advanced cancers, such as colorectal and breast cancers, suggest H2Bub1 and H2B ubiquitylation enzymes as cancer markers and novel targets for cancer therapy." (PMID 33199825, 2021). "RNF20 expression contributes to EMT induction and breast cancer progression through Snail-mediated epigenetic suppression of E-cadherin expression, suggesting the importance of RNF20 in breast cancer." (PMID 33364200, 2020). "Given the importance of RNF20 expression in breast cancer, we performed Kaplan-Meier analyses to determine the clinical relevance of RNF20 by analyzing a proteogenomic dataset that contains 65 breast tumor samples." (PMID 33364200, 2020). "Hypermethylation of the RNF20 promoter has also been discovered in primary breast cancers, consistent with a tumour suppressive role for RNF20." (PMID 33233707, 2020).
breast carcinoma (continued). "In this regard, the RNF20 promoter is hypermethylated in breast cancer and reduced expression of RNF20 and/or RNF40 is observed in seminoma, basal-like breast cancer, and colorectal cancer." (PMID 30781493, 2019). "For example, RNF20 represses the oncogene EZH2 in the basal breast cancer cell line HCC1937, while promoting its expression in the luminal breast cancer cell line MCF7." (PMID 30781493, 2019). "This therapeutic concern is supported by a recent report indicating that RNF20 differentially regulates multiple genes in basal-like breast cancer compared to luminal breast cancer." (PMID 30781493, 2019). "They discovered that a loss-of-function of RNF20/RNF40 resulted in G2/M arrest and apoptosis by downregulating the motor protein Eg5 in the human breast cancer cell line MCF-7." (PMID 31266541, 2019). "It was found that depletion of RNF20 increased breast cancer cell proliferation and migration potential." (PMID 29934362, 2018). "It is of note that RNF20 promotes CpG island hypermethylation in several breast cancers and that down-regulation of H2B ubiquitination promotes tumorigenesis." (PMID 29934362, 2018). "For example, the RNF20 promoter contains prominent CpG islands and is hypermethylated in human breast cancer." (PMID 29138263, 2017). "Corroborating this notion, the expression of RNF20/40 and Eg5 in these breast carcinoma samples was positively correlated." (PMID 27557628, 2016). "Our study uncovers an important spindle assembly role of the RNF20/40 complex, and implicates the RNF20/40-Eg5 axis in breast carcinogenesis, supporting the pursuit of these proteins as potential targets for breast cancer therapeutic interventions." (PMID 27557628, 2016). "In this study, we found that the expression of Eg5 and RNF20/40 are all elevated in breast carcinomas." (PMID 27557628, 2016). "The role of RNF20/40 and Eg5 in the growth and proliferation of breast cancer cells was then investigated." (PMID 27557628, 2016). "The interaction between the RNF20/40 complex and Eg5 was also detected in human breast carcinoma MCF-7 cells and human pancreatic carcinoma PANC-1 cells using co-immunoprecipitation assays." (PMID 27557628, 2016). "Other study suggests that the histone H2B ubiquitin ligase RNF20, a chromatin modifying enzyme and putative tumor suppressor, is an epigenetic target of resveratrol in breast cancer cells." (PMID 27355345, 2016). "We demonstrate that either RNF20/40 or Eg5 depletion in breast cancer cells inhibits breast cancer growth in athymic mice." (PMID 27557628, 2016). "Interestingly, RNF20 expression has previously been shown to be suppressed by promoter hypermethylation in breast cancers, making its reactivation and the restoration of H2Bub1 possible through the use of DNA methylation inhibitors." (PMID 37345659, 2023). "Significantly, Eg5 and RNF20/40 were concurrently upregulated in breast carcinomas, and higher Eg5 protein expression was correlated with poorer survival of breast cancer patients with luminal A or B type, implicating these proteins as potential targets for cancer treatment and prevention." (PMID 33199825, 2021). "Clinically, high RNF20 expression predicted shorter survival in breast cancer patients." (PMID 33364200, 2020). "RNF20 expression led to the inhibition of E-cadherin expression in the human breast cancer cells." (PMID 33364200, 2020). "Indeed, our studies showed that RNF20 expression significantly increased tumorigenicity in vitro, migration and invasion of breast cancer cells." (PMID 33364200, 2020). "As RNF20 expression contributes to the induction of EMT, we speculated that RNF20 expression might confer stem cell–like properties to breast cancer cells." (PMID 33364200, 2020). "Therefore at least in breast cancer, the role of RNF20 and H2Bub1 is highly dependent on cell type of origin; in fact this role is dichotomous in basal-like versus luminal breast cancer cells." (PMID 33233707, 2020).
breast carcinoma (continued). "Given the key roles of RNF20 in EMT, CSCs, and breast cancer, RNF20 may provide potential targets for controlling breast cancer progression." (PMID 33364200, 2020). "RNF20 expression enhanced breast cancer cell migration, invasion, tumorsphere and colony formation." (PMID 33364200, 2020). "Clearly, our study supports that RNF20 is crucial for the aggressiveness of breast cancer cells." (PMID 33364200, 2020). "Given the tight association of RNF20 with EMT, we hypothesized that RNF20 is critical for breast cancer cells migration and invasion." (PMID 33364200, 2020). "Collectively, these data suggest that RNF20 may induce EMT via the transcriptional suppression of E-cadherin expression in human breast cancer." (PMID 33364200, 2020). "As already noted, in vitro experiments interrogating cell migration and proliferation showed that depleting RNF20 that reduced H2Bub1 levels, acted to increase proliferation and migration of basal-like breast cancer cells, yet decreased these functional endpoints in luminal-type cells." (PMID 33233707, 2020). "These growth patterns were recapitulated in a mouse model, whereby down-regulation of RNF20 in basal-like cells resulted in faster growing mammary tumours relative to control cells, while down-regulation of RNF20 in luminal type cells led to slower growth than control cells." (PMID 33233707, 2020). "In an opposite fashion, upregulation of RNF20 leading to increased Hox gene expression may also contribute to a malignant phenotype, and knockdown of RNF20 in the breast cancer cell line MCF7 led to reduced proliferation." (PMID 30669413, 2019). "Here, silencing of RNF20 led to increased proliferation and migration in basal-like breast tumours, likely via upregulation of inflammatory cytokines, while silencing of RNF20 in luminal breast cancer cells decreased proliferation and migration, compromising transcription of the estrogen receptor." (PMID 30669413, 2019). "Silencing of RNF20 in breast cancer cells can function as a tumor promoter." (PMID 29934362, 2018). "Consistently, depletion of either RNF20/40 or Eg5 suppresses breast cancer in vivo." (PMID 27557628, 2016). "Moreover, our experiments also support pursuing the E3 ligase RNF20/40 as potential target for therapeutic intervention of breast cancer." (PMID 27557628, 2016). "Moreover, circRNF20 (hsa_circ_0087784), circulated from RNF20 gene exon-3 to exon-5, has been newly identified in breast cancer samples, and promotes the progress and glycolysis of breast cancer by abrogating the miR-487a-mediatied inhibition of the HIF-1α/HK2 axis." (PMID 35915091, 2022). "Furthermore, a recent study of different subtypes of breast cancer has shown that whether RNF20 and H2Bub1 inhibit or enhance cellular proliferation and migration is entirely dependent on the subtype." (PMID 30669413, 2019). "RNF20 and USP44 have different effects on the proliferation and migration of breast cancer cells dependent on subtype, i.e., basal-like versus luminal." (PMID 33233707, 2020). "Together, these observations indicate an important role for RNF20 in induction of EMT and acquisition of migratory and invasive ability in breast cancer cells." (PMID 33364200, 2020). "Down-regulation of RNF20 further increased the expression of IL6 and IL8 via NF-κB signalling in basal-like breast cancer cells and depleted the repressive chromatin mark H3K9me3 at their promoters." (PMID 33233707, 2020). "In this regard, high H2BK120ub1 levels and RNF20/RNF40 expression promote expression of ER target genes and proliferation of luminal breast cancer cells." (PMID 30781493, 2019). "The staining of Eg5 (median H score, 299), RNF20 (median H score, 274), and RNF40 (median H score, 272) was much stronger in 99 breast carcinoma tissues than the staining of these proteins in 10 adjacent normal breast tissues (median H score,<20)." (PMID 27557628, 2016).
breast carcinoma (continued). "In apparent contrast and already discussed in this review, a pro-oncogenic role for RNF20 has been reported in breast cancer cells of luminal, but not basal cell-type origin." (PMID 33233707, 2020). "Interestingly, in human breast cancer MCF7, MDA-MB-231, and T47D cell lines, RNF20/40 was found to be highly expressed compared with the normal human breast epithelial cell line MCF-10A." (PMID 29934362, 2018). "RNF20 knockdown significantly reduces H2Bub1 expression and promotes migration in both breast cancer cells and in non-transformed mammary epithelial cells." (PMID 29934362, 2018). "This suggests a concurrent upregulation of RNF20, RNF40, and Eg5 in breast cancer." (PMID 27557628, 2016).
colorectal cancer (7 papers, 2013 to 2025). A primary or metastatic malignant neoplasm that affects the colon or rectum. "The silencing of RNF20 contributed to inflammation-associated colorectal cancer by activating the NF-κB pathway." (PMID 35568845, 2022). "Previous studies showed that RNF20 was associated with histone H2B ubiquitination in inflammation-related colorectal cancer." (PMID 35568845, 2022). "In vivo RNF20+/− mice were shown to be predisposed to acute and chronic colonic inflammation and development of colorectal cancer." (PMID 29934362, 2018). "They showed that mice with reduced RNF20 and H2Bub1 are more susceptible to chronic colon inflammation and colorectal cancer, which is associated with activation of NF-κBp65 and reduced H3K9 trimethylation on a subset of NF-κB target genes." (PMID 29934362, 2018). "Using a model of Rnf20 heterozygous mice to drive depleted H2Bub1, as well as human samples of UC and colorectal cancer, Tarcic and colleagues have shown that loss of H2Bub1 creates a tumour promoting microenvironment in the colon centred on the chronic inflammatory response." (PMID 33233707, 2020). "In another apparent contrast, loss of RNF20 has been linked with an inflammatory phenotype in colorectal cancer, while loss of RNF40 would appear to have a protective effect against the development of an inflammatory phenotype in the same cancer, both involving NF-κB signalling." (PMID 30669413, 2019). "Our study indicated that RNF38 exhibited a negative effect on growth and metastasis in NPC by suppressing NF-κB and MAPK activation instead of activating the NF-κB pathway by RNF20 or RNF183 in colorectal cancer." (PMID 35568845, 2022). "The human genes SMC1, SMC3, NIPBL, STAG3, RNF20, FBXW7/CDC4, MRE11A, RAD54B and BLM have been found to be mutated in colorectal cancer, and together account for approximately 25% of the CIN mutational spectrum of this disease." (PMID 23382697, 2013). "A low frequency of RNF20 and RNF40 mutations have been reported in colorectal cancer." (PMID 33233707, 2020).
leukemia (7 papers, 2016 to 2025). A malignant (clonal) hematologic disorder, involving hematopoietic stem cells and characterized by the presence of primitive or atypical myeloid or lymphoid cells in the bone marrow and the blood. "Suppression of RNF20 slowed down leukemia progression in an in vivo animal model and was associated with down-regulation of the MLL-AF9 target gene." (PMID 29934362, 2018). "In mixed lineage leukemia (MLL)-rearranged leukemia, RNF20 expression also promotes cell proliferation, and RNF20-mediated H2BK120ub1 is enriched within the body of MLL-fusion target genes and promotes their expression." (PMID 30781493, 2019). "They found that RNF20 is an additional chromatin regulator that is necessary for MLL-fusion-mediated leukemogenesis and that suppression of RNF20 in leukemia cells leads to inhibition of cell proliferation in vitro." (PMID 29934362, 2018). "Conversely, RNF20 promotes oncogenic transcriptional program in leukemia in which SREBP and fatty acid biosynthesis are suppressed." (PMID 29138263, 2017). "(2013) they reported the role of RNF20 in the pathogenesis of MLL-fusion leukemia." (PMID 29934362, 2018). "The suppression of RNF20 in diverse models of MLL-rearranged leukemias resulted in reduced H3K79 methylation by DOT1L and the inhibition of cell proliferation, suggesting that reducing RNF20-mediated H2B ubiquitination induces an antileukemic effect." (PMID 35331314, 2022). "In summary, RNF20 is a possible therapeutic target in MLL-rearranged leukemias, but this method faces many challenges; for example, the therapeutic effect of RNF20 inhibition is sometimes not obvious." (PMID 35331314, 2022).